IL18 (interleukin 18)
Diseases named in the same sentence as IL18 in open-access papers (continued):
Sharing a sentence is not in itself a finding about the gene and the disease.
colitis (continued). "In the present study, we showed that MitoQ suppresses ROS-promoted dissociation of TXNIP from TRX, inhibits the interaction between TXNIP and NLRP3, and significantly decreases levels of IL-1 beta and IL-18 in the colons of mice with DSS-induced colitis." (PMID 23915129, 2013). "Animal models of IBD have provided a critical tool to mechanistically determine the potential role of IL-18 during the pathogenesis of colitis." (PMID 23847622, 2013). "We showed that MitoQ ameliorates acute colonic injury in a mouse model of colitis not only by its antioxidative effects but also by anti-inflammatory effects that suppress the maturation of pro-inflammatory cytokines IL-1 beta and IL-18." (PMID 23915129, 2013). "In mice with either 2,4,6-trinitrobenzene sulfonic acid (TNBS)- or DSS-induced colitis, intestinal IL-18 levels of both macrophage and epithelial cell origin were found to be markedly elevated." (PMID 23847622, 2013). "Since generation of active IL-18 requires caspase-1, studies have also been performed in mice deficient in caspase-1 and subjected to DSS colitis." (PMID 24115947, 2013). "Mice deficient in caspase-1 experience increased disease severity when subjected to DSS colitis and that administration of exogenous IL-18 restored mucosal healing in these mice." (PMID 24115947, 2013). "Furthermore, IL-18 has been shown to be essential for mucosal homeostasis: mice deficient in Nlrp3, Pycard/Asc, caspase-1, IL-18, or IL-18R—all components of the inflammasome pathway—are highly susceptible to DSS-induced colitis." (PMID 40869366, 2025). "Since IL-18- and IL-18R-deficient mice are more susceptible to DSS than their wildtype littermates, IL-18—released from intestinal epithelial cells—appears to protect against colitis by promoting tissue repair and maintaining intestinal lining homeostasis." (PMID 40869366, 2025). "However, excessive IL18 signaling in intestinal epithelial cells (IECs) disrupts goblet cell maturation and exacerbates colitis." (PMID 41133791, 2025). "To investigate whether the exacerbation of dextran sulfate sodium (DSS)-induced colitis by inulin supplementation via IL-18, we first evaluated the expression levels of IL-18 in serum during inulin feeding." (PMID 41133791, 2025). "Moreover, the exacerbation of colitis was abolished in IL-18 knockout mice, indicating a critical role for inflammasome signaling in mediating this response." (PMID 41133791, 2025). "Furthermore, MHV-68 infection activated pyroptosis by upregulating gasdermin D, NLRP3, interleukin-1β, and interleukin-18 in colonic tissues and peritoneal macrophages of mice with colitis." (PMID 40041420, 2025). "Activation of caspase-1, a key effector of the inflammasome complex, has been observed to contribute to CD4 T cell depletion during HIV infection, while blocking IL-18 signaling in T cells may exacerbate disease severity in murine colitis models." (PMID 40530419, 2025). "Moreover, active IL-1β and IL-18 levels are associated with increased FLC, along with more severe colitis damage and tumor formation." (PMID 40806736, 2025). "Increased IL‐18 expression contributes to the progression of TNBS‐induced colitis." (PMID 39119947, 2024). "Thus, blocking IL-1β and IL-18 would be one of the plausible approaches for the treatment of colitis accompanying pyroptosis." (PMID 38491049, 2024). "During colitis, the release of several proinflammatory mediators, such as IL-6, IL-18, IL-22, and RELMβ, has been shown to enhance the intestinal epithelial cells proliferation, induce the release of antimicrobial peptides and anti-inflammatory mediators and promote the mucosa wound healing." (PMID 39684467, 2024). "Predicted upstream regulators of ILCs in CPI-C included Tbx21, encoding the transcription factor T-bet, and genes encoding the cytokines Il2, Il18 and Il21, suggesting that ILC1 may contribute to colitis in this model." (PMID 39496592, 2024).
colitis (continued). "In addition, DEGs associated with the immune receptor (Lrrc19), cell chemotaxis (Ccr7, Cxcl1, Cxcl5, Cxcl9, and Cxcl10), and inflammatory response (IL1r11, IL11, Tnf, IL1β, and IL18) were also upregulated in the colonic tissue of colitis mice in DVF group." (PMID 38172943, 2024). "Further, NLRP1 activated IL-18 contributes to DSS-induced colitis phenotype." (PMID 38455052, 2024). "Taken together, KLPJ-mediated colitis mainly depends on IL18 derived from colon epithelial cells." (PMID 36436756, 2023). "In a model of colitis, it was observed that the absence of Casp11 impaired IL-18 production, increasing susceptibility to colitis." (PMID 37564649, 2023). "However, decreased IL-18 production from colonic epithelia is related to more severe colitis indicating the potential anti-inflammatory effect of IL-18." (PMID 36932407, 2023). "A marked difference existed in the KLPJ-mediated colitis between the WT and IL18 KO mice." (PMID 36436756, 2023). "All of these results suggest that KLPJ-mediated colitis depends on IL18." (PMID 36436756, 2023). "Epithelial IL-18 may be beneficial, while IL-18 produced by LP cells may be detrimental to barrier function in colitis." (PMID 37240022, 2023). "IL-18 was also demonstrated to protect against colitis in a previously reported mouse model." (PMID 37910490, 2023). "Inhibition or knockdown of the NLRP3 inflammasome could alleviate the severity of DSS-induced colitis, control the release of IL-1β and IL-18, and suppress the inflammatory response of UC." (PMID 36762118, 2023). "By contrast, IL-18 treatment at a later stage of the disease enhanced inflammatory infiltration and reduced Muc-2 expression, decreased the function and quantity of goblet cells, suggesting the anti-inflammatory effect of IL-18 at the early stage of colitis-induced inflammation." (PMID 37383609, 2023). "In addition, in the oxazolone-induced mouse UC model, NLRP3 knockout mice have more severe colitis, as indicated by increased Th2 cytokine expression and decreased production of mature IL-1β and IL-18." (PMID 37370025, 2023). "Here, we found that isolated K pneumoniae from the colon tissue of patients with UC could induce colitis and promote dextran sodium sulfate (DSS)-mediated colitis through caspase-11–mediated IL18." (PMID 36436756, 2023). "Interestingly, continuous suppression of IL-18 using a vaccine improves intestinal inflammation in TNBS-induced murine colitis." (PMID 38137450, 2023). "This strain of bacteria could induce the production of mature IL18 in colon epithelial cells and gut organoids, and also induce colitis and promote dextran sodium sulfate–mediated colitis." (PMID 36436756, 2023). "We also observed the effects of KLPJ on DSS-mediated colitis in IL18 KO mice." (PMID 36436756, 2023). "In addition, MCC950, a chemical NLRP3 inhibitor, can significantly suppress the release of the pro-inflammatory cytokines IL-1β, IL-18, and IL-1α in colitis." (PMID 37240022, 2023). "In this respect, it could be concluded that the equilibrium between epithelial IL-18 and LP-produced IL-18 is critical for barrier function in colitis." (PMID 37240022, 2023). "Overall, these results suggest that the excessive production of IL-1β and IL-18 following upregulated activation of inflammatory caspases in the LP could explain the exacerbation of VAD DSS-induced colitis." (PMID 37240022, 2023). "Importantly, the anti-inflammatory effects of IL-18 were observed in the early stage of DSS-induced colitis, while the proinflammatory effects were observed in the later stages of the disease." (PMID 38137450, 2023). "In the homeostatic condition, IECs-derived IL-18 is dispensable for Tregs differentiation, but Tregs-mediated suppression of intestinal inflammation requires IL-18/IL-18R1 signaling in the T cell-transfer colitis model." (PMID 35844606, 2022). "In addition, IL-18 overproduction in the mucosa exacerbated infiltration of macrophages and colitis in mouse models of gut inflammation." (PMID 36313762, 2022).
colitis (continued). "Unsurprisingly, IL‐18 is heavily involved in colitis pathology." (PMID 35593111, 2022). "Therefore, more severe colitis symptoms were detected in IL-37tg mice, perhaps because abundant IL-37 in colon inhibited IL-18–mediated cytoprotective effects in the DSS model." (PMID 35046386, 2022). "Similarly, mice deficient in the AIM2 inflammasome had few colonic levels of IL-18, low expression of AMP, and were highly susceptible to colitis and microbiota dysbiosis (in particular Escherichia coli enrichment)." (PMID 36313762, 2022). "In addition, DSS colitis was minimally suppressed in experimental mice using antimurine IL-18 antiserum." (PMID 36032110, 2022). "Furthermore, IL-18 can reduce cell proliferation in the intestinal epithelium at the tumor zone in the colitis remission phase." (PMID 36389791, 2022). "A more precise study using IEC‐specific IL‐18/IL‐18R1‐deficient mice and IL‐18 bp‐deficient mice revealed that IL‐18 derived from endothelial cells and/or hematopoietic cells (presumably including IMφs) aggravated DSS colitis development by disrupting goblet cell maturation." (PMID 35593111, 2022). "Furthermore, in a murine model of colitis, a significantly lower level of IL-18 was found after apremilast treatment, which is consistent with our data." (PMID 34884681, 2021). "Instead, IL‐18 activation by NLRP1 contributes to DSS‐induced colitis phenotype." (PMID 34705319, 2021). "Therefore, the use of chemical inhibitors of caspase-1, IL-1β and IL-18 can help to understand the exact role of these molecules in colitis pathogenesis." (PMID 34571825, 2021). "However, it has also been found that the IL-1β and IL-18 produced by NLRP3 inflammatory complexes have protective effects against colitis, although the mechanism is still unclear." (PMID 34462641, 2021). "A more recent study claimed that IL-18 produced by the enteric nervous system is essential for protection against bacterial infection via goblet cell antimicrobial peptide production, indicating a divergent role of IL-18 in colitis." (PMID 34948435, 2021). "Exogenous IL-18 increased colonic injury in Gsdmd-/- mice during DSS-induced colitis." (PMID 34721422, 2021). "Thus, GSDMD promotes colitis development by mediating IL-18 release, and the microbiota can mediate colitis pathogenesis through regulation of GSDMD activation." (PMID 34721422, 2021). "Butyrate combines with GPR43 to stimulate potassium ion flow, which leads to a hyperpolarisation of the intestinal epithelial cell membrane, activation of the NLRP3 inflammasome, and upregulation IL-18, thus maintaining intestinal epithelial integrity and mucosal homeostasis in mice with colitis." (PMID 34733901, 2021). "Moreover, NLRP3 inflammasome-derived IL-1β and IL-18 play a protective role against oxazolone-induced colitis, and a hyperactive NLRP3 inflammasome (such as that in the Nlrp3 R258W mutant mouse line) confers strong resistance to experimental colitis/CRC." (PMID 34064909, 2021). "Furthermore, we found that PHLPP2−/− mice developed hypersensitivity to dextran sulfate sodium (DSS) treatment toward colitis showing activated NF-κB signaling and dramatically induced expressions of caspase-1 P20, Gasdermin N, IL-18, and IL-1β." (PMID 34394827, 2021). "Since IL-18 has been previously shown to ameliorate severity of DSS colitis, we aimed to determine whether IL-18 supplementation would be sufficient to reduce inflammation in Prevotella-colonized mice." (PMID 32433514, 2021). "IL-18 promotes the expression of anti-microbial peptide and alleviates colitis." (PMID 34733901, 2021). "Some of this evidence suggests that after colitis occurs, the production of IL-1β, IL-18, and anti-inflammatory cytokines IL-10 and TGF-β decreases in Nlrp3−/− mice, which may in turn hinder repair mechanisms and increase intestinal epithelial permeability." (PMID 33227973, 2020).
colitis (continued). "IL-18 has been demonstrated to be an important regulatory protein in the homeostatic and pathophysiological context as its decrease is associated with reduction in the severity of DSS-induced colitis." (PMID 33121008, 2020). "Additionally, IL-18-/- mice have been shown to develop more severe DSS-induced colitis than WT mice." (PMID 32545788, 2020). "Importantly, inhibition of Cbl with hydrocotarnine increases inflammasome-mediated IL-18 secretion in the colon and protects mice from dextran sulphate sodium-induced colitis." (PMID 32707731, 2020). "However, sinapic acid treatment also decreased the serum and colonic levels of IL-1β and IL-18, which were associated with decreased NLRP3, ASC, and caspase-1 protein levels in the colons of colitis mice." (PMID 33312339, 2020). "IL-18 is involved in homeostatic renewal of the gut epithelial barrier, to prevent colitis." (PMID 33255437, 2020). "Indeed, IL-18-/- mice show an increased incidence of polyps, colitis and colorectal cancers, therefore illustrating its role in cancer protection under steady state conditions." (PMID 33255437, 2020). "Moreover, in a rodent model, the deletion of Chga ameliorates DSS-induced colitis by reducing the colonic expression of collagen, IL-18, by maintaining the epithelial barrier’s function and preserving the decrease of TJ proteins’ expression." (PMID 33121008, 2020). "In animal studies, IL-18 levels are significantly increased in experimental colitis." (PMID 31428451, 2019). "Interestingly, deficiency in the NLRP6 inflammasome is detrimental in DSS-induced colitis, in a manner related to insufficient IL-18." (PMID 31139196, 2019). "Given the essential role for caspase-11 and the non-canonical inflammasome in the regulation of IL-18 production during DSS-colitis, we hypothesised that caspase-11 may also be essential for the production of intestinal IL-18 and IL-1β during CAC." (PMID 30538296, 2019). "However, the concept of detrimental inflammasome signaling in IBD is being re-evaluated due to recent reports that IL-1β and IL-18 production can confer protection against colitis." (PMID 30873162, 2019). "Our results showed that immunization of mouse with IL-18 peptide-based vaccine could improve murine colitis, which indicated this vaccine strategy might be a potential treatment approach." (PMID 31428451, 2019). "This approach led to the identification of at least 4 highly IBD phenotype-associated loci, with strongest evidence for a locus spanning genes for IL-10 receptor alpha and IL-18, and this locus overlaps with susceptibility loci discovered in the DSS and TNBS colitis models." (PMID 31015842, 2019). "Furthermore, in the colitis remission phase IL-18 can reduce cell proliferation in the intestinal epithelium at the tumor zone." (PMID 30447690, 2018). "We have shown that IL-18 is involved in the exacerbation of DSS-colitis after activation of NLRP1." (PMID 30214011, 2018). "Moreover, IL-18 neutralization or pralnacasan inhibition of Caspase-119,20 effectively reduced severity in murine colitis." (PMID 29872077, 2018). "Furthermore, in vivo neutralization of IL-18 with neutralizing antibodies, IL-18BP or anti-sense oligos ameliorates inflammation in murine models of colitis." (PMID 29601578, 2018). "In DSS-induced colitis the epithelial barrier defenses are defective, and treatments used to reduce and or to block IL-18, through neutralizing monoclonal antibody or binding protein, induce a protective mechanism associated with a decrease in pro-inflammatory mediators." (PMID 30241336, 2018). "IL-18 shows protective effects in DSS-induced colitis models." (PMID 28360909, 2017). "Indeed, although caspase-11 has been proposed to mediate a protective role in the host during the acute phases of colitis, it appears to be detrimental in chronic inflammation, where it is significantly upregulated and promotes IL-1β and IL-18 release." (PMID 28179906, 2017).
colitis (continued). "Furthermore, similar antioxidant MitoQ mitigated symptoms of experimental colitis, which is governed, at least partially, by the prevention of IL-1β and IL-18 release." (PMID 29158874, 2017). "Indeed, blocking IL-18 signaling protected mice against colitis mediated by transfer of naive T cells into lymphopenic hosts." (PMID 28979266, 2017). "However, several recent studies demonstrated that IL-18 derived from the NLRP3 inflammasome suppresses experimental colitis." (PMID 27966619, 2016). "In contrast to IL-18, less attention has been focused on the role of IL-1β in colitis." (PMID 27966619, 2016). "Although deficiency in other inflammasome components, including ASC, caspase-1, and IL-18, also led to dysbiosis and exacerbated colitis, deficiency in NLRC4, NLRP10, NLRP12, and AIM2 had no impact on the susceptibility of WT mice to colitis upon cohousing." (PMID 26925061, 2016). "However, during DSS colitis, intestinal upregulation of IL-18 expression appears to be regulated by caspase-11." (PMID 25548224, 2015). "Our study links caspase-11–mediated IL-18 production to the increased susceptibility of Casp11−/− mice to colitis, suggesting the involvement of noncanonical inflammasomes in IEC proliferation, inhibition of cell death, and epithelial barrier function." (PMID 25548224, 2015). "Histological analysis of H&E-stained colons revealed significant protection of crypt architecture in IL-18– compared with PBS-treated Casp11−/− mice with DSS-induced colitis, which is consistent with a specific role for IL-18 in intestinal epithelial regeneration and repair in this disease model." (PMID 25548224, 2015). "Equally, lack of epithelial IL-18 expression in NLRP3 deficient mice enhanced susceptibility of these mice to DSS-induced colitis when compared to control wild-type mice." (PMID 24886810, 2014). "These NLPRs are correlated with lower IL-1β and IL-18 production during colitis." (PMID 25309932, 2014). "Interestingly, epithelial-derived IL-18 is also critical for protection against DSS colitis conferred by NLR-mediated signaling, as shown in studies using NLRP3 deficient mice." (PMID 25071778, 2014). "Therefore, NLRP6 participates in the steady-state regulation of the commensal microbiota and appears to be essential for preventing recurring colitis through the induction of basal secretion of IL-18 by epithelial cells." (PMID 25309932, 2014). "In the context of DSS colitis models, the role of IL-18 and IL-1β is still a matter of debate." (PMID 23606794, 2013). "However, other studies have shown exactly the opposite—that transgenic or pharmacological blockage of IL-1β converting enzyme (ICE) or IL-18 ameliorate DSS colitis." (PMID 23606794, 2013). "Furthermore, administration of exogenous IL-18 can alleviate the severity of colitis and colitis-induced tumorigenesis in caspase-1/11 and Nlrp3 KO mice." (PMID 23847622, 2013). "We next asked whether an activated inflammasome leads to enhanced release of IL-1 beta and IL-18 during colitis." (PMID 23915129, 2013). "In addition, scavenging mtROS by MitoQ resulted in a significant decrease of IL-1 beta and IL-18 in DSS-induced colitis." (PMID 23915129, 2013). "These contradictory results could be attributed to the multifunctional role of IL-18 in colitis." (PMID 37240022, 2023). "After induction of colitis by DSS, there was weight loss, diarrhea, fecal bleeding, increased mortality, ulcers, loss of colon, and inflammation configured by cellular infiltration, the elevation of pro-inflammatory cytokines (IL-1β, IL-18, TNF-α, and IL-6) and NO." (PMID 36677021, 2023). "This pathway and associated inflammatory markers could be relevant in colitis as NLRP3 inflammasome activity (critical for caspase 1-dependent release of IL-1β and IL-18) in the CNS has been implicated in the exacerbation of neuroinflammation by DSS-induced colitis in aging mice." (PMID 34983592, 2022).